KLRF1 (killer cell lectin like receptor F1)
Description:
Functions as an activating receptor involved in immunosurveillance upon binding to various ligands displayed at the surface of myeloid cells. Upon interaction with CLEC2B ligand, stimulates NK-cell cytotoxicity and cytokine production leading to the cytolysis of malignant CLEC2B-expressing myeloid cells. Actviation of the common cytotoxicity pathway involves SRC and SYK kinases.
Synonyms: CLEC5C; NKp80
Tractability: Antibody: its Gene Ontology location is reachable by antibodies, with high confidence; UniProt predicts a signal peptide or a membrane-spanning region; the Human Protein Atlas places it where antibodies can reach.
Gene: Protein-coding gene on chromosome 12 (9,827,481 to 9,845,007, forward strand). Ensembl gene ENSG00000150045.
Subcellular location: Membrane
Subcellular location (Human Protein Atlas): Plasma membrane
Pathways (Reactome):
Immune System: Immunoregulatory interactions between a Lymphoid and a non-Lymphoid cell
Gene Ontology:
Molecular function: transmembrane signaling receptor activity; MHC class I receptor activity
Biological process: NK T cell activation; cell surface receptor signaling pathway
Cellular component: membrane; plasma membrane
Genetic constraint (gnomAD): Loss-of-function variants: 6 observed, 14.01 expected, observed/expected ratio (o/e) 0.43, 90% interval 0.23 to 0.85. The upper end of that interval is the gene's LOEUF score, 0.85, which puts it in group 3 of 6, group 1 being the genes least tolerant of losing a copy. Missense variants: 113 observed, 121.91 expected, observed/expected ratio (o/e) 0.93, 90% interval 0.8 to 1.08. Synonymous variants: 43 observed, 39.72 expected, observed/expected ratio (o/e) 1.08, 90% interval 0.85 to 1.4.
Homologues: Orthologues: chimpanzee KLRF1 (98% identical), macaque KLRF1 (90% identical), dog KLRF1 (78% identical), pig KLRF1 (74% identical), zebrafish si:ch211-193e13.5 (19% identical), zebrafish si:ch211-170d8.8 (18% identical), Caenorhabditis elegans clec-146 (15% identical), zebrafish si:dkey-26c10.5 (13% identical), Drosophila melanogaster rgn (13% identical), Caenorhabditis elegans clec-196 (10% identical). Paralogues in human: CLEC9A (24% identical), KLRG1 (23% identical), CLEC1B (23% identical), CLEC12B (22% identical), KLRB1 (22% identical), CLEC7A (21% identical), KLRF2 (20% identical), CLEC1A (19% identical), OLR1 (19% identical), KLRC1 (19% identical), KLRC2 (18% identical), KLRC3 (18% identical), and 11 more.
Diseases named in the same sentence as KLRF1 in open-access papers:
KLRF1 is named in the same sentence as 34 diseases in open-access papers, as found by Europe PMC text mining. Sharing a sentence is not in itself a finding about the gene and the disease. The quoted sentences say what the papers report.
psoriasis (2 papers, 2010 to 2025). An autoimmune condition characterized by red, well-delineated plaques with silvery scales that are usually on the extensor surfaces and scalp. "In psoriasis, CCL4, GZMK and KLRF1 show significantly higher, while ADM, ANXA3, IL4, MMP9 and OLR1 show significantly lower expression levels in patients with arthritis negative psoriasis compared to patients with symptoms of arthritis." (PMID 20444268, 2010).
viral infections (2 papers, 2021 to 2022). "Four subsets strongly expressed KLRF1 and FCGR3A, displayed surface expression of CD161 and resembled a population of CD16+ CD8+ T cells that has previously been described in other viral infections." (PMID 36591270, 2022).
Autoimmunity (1 paper, 2024). The occurrence of an immune reaction against the organism's own cells or tissues. "KLRF1 suppresses NK cells and monocytes by interacting with MHC class I ligands to influence autoimmunity." (PMID 38774864, 2024).
bladder cancer (1 paper, 2023). "KLRF1 is a surrogate marker of CD56bright NK cells and is a potential prognostic marker in bladder cancer." (PMID 36583228, 2023). "KLRF1 is a promising prognostic marker in bladder cancer and may guide treatment decisions upon validation." (PMID 36583228, 2023). "The functional significance of KLRF1 in bladder cancer NK cells is unknown." (PMID 36583228, 2023).
bladder tumors (1 paper, 2023). "In contrast, KLRF1 is a marker of bladder tumor‐infiltrating‐activated CD56bright NK cells and is associated with improved survival for patients with invasive bladder cancer." (PMID 36583228, 2023). "Thus, high KLRF1 gene expression potentially marks more mature and activated NK cells in bladder tumors, supported by the strong association of high KLRF1 with improved survival." (PMID 36583228, 2023). "TCGA analysis revealed that patients with high KLRF1 bladder tumor expression had significantly improved RFS (p = 0.02), CSS (p = 0.02), and OS (p = 0.03) compared to patients with tumors expressing low levels of KLRF1." (PMID 36583228, 2023). "We next sought to examine the prognostic significance of bladder tumor KLRF1." (PMID 36583228, 2023).
COVID-19 (1 paper, 2022). A disease caused by infection with severe acute respiratory syndrome coronavirus 2. "Comparison between the disease conditions indicated significantly stronger expression of certain NK cell receptors (CD160, KLRC2, KLRC3, KLRF1, KIR3DL2, NCR1, NCR3) along the SLEC lineage in mild COVID-19 compared to severe COVID-19." (PMID 36591270, 2022).
gastric cancer (1 paper, 2023). A primary or metastatic malignant neoplasm involving the stomach.
idiopathic pulmonary fibrosis (1 paper, 2024). Idiopathic pulmonary fibrosis (IPF) is a nonneoplastic pulmonary disease that is characterized by the formation of scar tissue within the lungs in the absence of any known cause. "We identified one transcript, killer cell lectin like receptor 1 (KLRF1), as differentially expressed between idiopathic pulmonary fibrosis (IPF) and systemic sclerosis-associated ILD (SSc-ILD), and identified two transcripts (VCAN, LTK) associated with IPF expression against other ILD subtypes." (PMID 39625896, 2024).
tumor (12 papers, 2012 to 2025). "Blocking of the interaction of AICL and KLRF1 led to a partial inhibition of NK cell degranulation, showing that these receptors play a key role in the killing of tumor cell by NK-cells." (PMID 31993369, 2019). "However, the magnitude of the association of KLRF1 with survival was not modified by tumor MHC I as the interaction term KLRF1‐MHC I was not significant in multivariable models of RFS, CSS, and OS (p ≥ 0.70)." (PMID 36583228, 2023). "High KLRF1 expression was also significantly associated with improved RFS (HR = 0.53, p = 0.01), CSS (HR = 0.47, p = 0.02), and OS (HR = 0.54, p = 0.02) on multivariable analysis that included patient age, gender, pathologic stage, tumor MHC I, and tumor molecular subtype." (PMID 36583228, 2023). "However, mesothelial and NK cell markers found in the MPE were largely absent across the primary tumour dataset (DES and KLRF1), reflecting the unique aspects of the pleural microenvironment." (PMID 37691350, 2023).
cancer (2 papers, 2022 to 2023). A tumor composed of atypical neoplastic, often pleomorphic cells that invade other tissues. "High intratumoral KLRF1 was associated with improved recurrence‐free survival (hazard ratio [HR] 0.53, p = 0.01), cancer‐specific survival (HR 0.47, p = 0.02), and overall survival (HR 0.54, p = 0.02) on multivariable analyses that adjusted for clinical and pathologic variables." (PMID 36583228, 2023).
KLRF1 also shares sentences with these, for which no sentence is quoted: infection (3 papers); malaria (2); osteoporosis (2); acute lymphoblastic leukemia (1); acute myeloid leukemia (1); allergic rhinitis (1); Angina (1); Arthritis (1); bacterial infections (1); Burkitt lymphoma (1); cervical cancer (1); HIV-1 infection (1); hypersensitivity pneumonitis (1); leukemia (1); lymphoma (1); myeloid leukemia (1); myocarditis (1); nephritis (1); non-small cell lung carcinoma (1); osteosarcoma (1); pancreatic cancer (1); squamous intraepithelial lesions (1); systemic sclerosis (1); T-cell acute lymphoblastic leukemia (1).